ALDH1A2 (aldehyde dehydrogenase 1 family member A2)
Description:
Catalyzes the NAD-dependent oxidation of aldehyde substrates, such as all-trans-retinal and all-trans-13,14-dihydroretinal, to their corresponding carboxylic acids, all-trans-retinoate and all-trans-13,14-dihydroretinoate, respectively. Retinoate signaling is critical for the transcriptional control of many genes, for instance it is crucial for initiation of meiosis in both male and female (Probable). Recognizes retinal as substrate, both in its free form and when bound to cellular retinol-binding protein (By similarity). Can metabolize octanal and decanal, but has only very low activity with benzaldehyde, acetaldehyde and propanal (By similarity). Displays complete lack of activity with citral (By similarity).
Synonyms: RalDH2; RALDH(II); DIH4; RALDH2-T
Tractability: Small molecule: a structure with a bound ligand is known; a high-quality ligand is known; it belongs to a druggable protein family. PROTAC: ubiquitination databases record sites on it; its protein half-life has been measured; a small molecule that binds it is known.
Target class: Enzyme; Oxidoreductase
Gene: Protein-coding gene on chromosome 15 (57,953,424 to 58,497,866, reverse strand). Ensembl gene ENSG00000128918.
Subcellular location: Cytoplasm
Pathways (Reactome):
Signal Transduction: RA biosynthesis pathway
Gene Ontology:
Molecular function: retinal dehydrogenase (NAD+) activity; 3-chloroallyl aldehyde dehydrogenase activity; aldehyde dehydrogenase (NAD+) activity; retinal binding; oxidoreductase activity
Biological process: negative regulation of cell population proliferation; neural tube development; protein homotetramerization; response to cytokine; response to retinoic acid; retinoic acid biosynthetic process; retinoic acid metabolic process; 9-cis-retinoic acid biosynthetic process; aldehyde metabolic process; vitamin A metabolic process; cellular response to retinoic acid; kidney development; liver development; midgut development; pituitary gland development; response to estradiol; response to vitamin A; retinol metabolic process
Cellular component: cytoplasm; cytosol; perinuclear region of cytoplasm
Genetic constraint (gnomAD): Loss-of-function variants: 26 observed, 62.06 expected, observed/expected ratio (o/e) 0.42, 90% interval 0.31 to 0.58. The upper end of that interval is the gene's LOEUF score, 0.58, which puts it in group 2 of 6, group 1 being the genes least tolerant of losing a copy. Missense variants: 581 observed, 675.43 expected, observed/expected ratio (o/e) 0.86, 90% interval 0.8 to 0.92. Synonymous variants: 289 observed, 245.47 expected, observed/expected ratio (o/e) 1.18, 90% interval 1.07 to 1.3.
Homologues: Orthologues: chimpanzee ALDH1A2 (99% identical), dog ALDH1A2 (99% identical), macaque ALDH1A2 (99% identical), rabbit ALDH1A2 (98% identical), rat Aldh1a2 (97% identical), mouse Aldh1a2 (97% identical), pig ALDH1A2 (95% identical), guinea pig ALDH1A2 (91% identical), tropical clawed frog aldh1a2 (91% identical), zebrafish aldh1a2 (79% identical), Caenorhabditis elegans alh-1 (60% identical), Caenorhabditis elegans alh-2 (58% identical), and 3 more. Paralogues in human: ALDH1A1 (70% identical), ALDH1A3 (69% identical), ALDH2 (66% identical), ALDH1B1 (64% identical), ALDH1L1 (50% identical), ALDH1L2 (48% identical), ALDH9A1 (38% identical), ALDH8A1 (35% identical), ALDH5A1 (34% identical), ALDH7A1 (30% identical), ALDH6A1 (30% identical), ALDH4A1 (28% identical), and 5 more.
Diseases named in the same sentence as ALDH1A2 in open-access papers:
ALDH1A2 is named in the same sentence as 127 diseases in open-access papers, as found by Europe PMC text mining. Sharing a sentence is not in itself a finding about the gene and the disease. The quoted sentences say what the papers report.
ovarian carcinoma (19 papers, 2009 to 2025). A malignant neoplasm originating from the surface ovarian epithelium. "A low level of expression of ALDH1A2 has been associated with a poor prognosis and shorter disease-free and overall survival for ovarian cancer patients." (PMID 36768694, 2023). "Low ALDH1A2 expression is associated with poor prognosis and shorter disease-free and overall survival for ovarian cancer patients." (PMID 36651035, 2023). "Low ALDH1A2 expression was associated with unfavorable prognosis and shorter disease-free and overall survival for ovarian cancer patients." (PMID 31615043, 2019). "Five of the 10 most down-regulated genes, Aldh1a2, Enpp2, Lgfbp5, Thbd, and Uchl1, have been previously implicated in ovarian cancer." (PMID 24672774, 2014). "Previous studies have shown that ALDH1A2 is a candidate tumor suppressor gene in ovarian cancer and enhancing ALDH1A2-linked signaling might provide new opportunities for therapeutic intervention." (PMID 34928471, 2022). "Although we observed the epigenetic regulation of ALDH1A2, the underlying mechanism of the correlation between low ALDH1A2 expression and aggressive disease in ovarian cancer remains unclear." (PMID 31615043, 2019). "However, the detailed mechanism underlying the link between ALDH1A2 methylation and ovarian cancer progression requires further investigation." (PMID 31615043, 2019). "However, only the loss of DNMT1 or DNMT3B significantly restored the ALDH1A2 expression in ovarian cancer cell lines." (PMID 31615043, 2019). "Therefore, the methylation-silenced expression of ALDH1A2 may be responsible for lower RA levels and altered RA-linked signaling, contributing to the development of ovarian cancer progression." (PMID 31615043, 2019). "Conversely, the ALDH1 isoform ALDH1A2 has been suggested to act as a tumor suppressor in ovarian cancer, where its expression is significantly reduced, correlating with poor patient prognosis." (PMID 39781359, 2025). "In epithelial ovarian cancer, ALDH1A2 suppresses signal transducer and activator of transcription 3 (STAT3) signaling, a pathway known to promote tumor proliferation and migration." (PMID 39781359, 2025). "From complementary DNA microarray data, ALDH1A1 was downregulated in human ovarian cancer cell line cells, and hypermethylation of ALDH1A2 was higher in the cancer cell lines than in immortalised human ovarian epithelial cell lines." (PMID 36768694, 2023). "delineated that ALDH1A2 is the most prominently downregulated gene among ALDH family members in ovarian cancer cells, based on microarray analysis." (PMID 36694633, 2023). "When ovarian cancer cell lines were compared to immortalized human ovarian surface epithelial cells, hypermethylation of the ALDH1A2 gene was higher in the cancer cell lines." (PMID 37569466, 2023). "A study showed that up-regulated ALDH1A2 suppressed ovarian cancer cell proliferation via activation of transcription 3 (STAT3)." (PMID 36287961, 2022). "Previous studies have demonstrated ALDH1A2 to be a candidate tumor suppressor in several human malignancies, including prostate, head and neck, ovarian cancer." (PMID 34745985, 2021). "The overexpression of ALDH1A2 also suppressed the proliferation and invasive ability of ovarian cancer cells." (PMID 31615043, 2019). "Here, we found that ALDH1A2 was the most prominently downregulated gene among ALDH family members in ovarian cancer cells, according to complementary DNA microarray data." (PMID 31615043, 2019). "Here, we showed that a low level of ALDH1A2 expression in ovarian cancer was correlated with hypermethylation of the gene." (PMID 31615043, 2019). "Methylation-specific PCR analysis revealed that the methylation of ALDH1A2 was markedly higher in ovarian cancer cell lines (RMG1, SKOV3, and OVCA433) than in IHOSE8695 cells." (PMID 31615043, 2019). "In these studies, we found that low ALDH1A2 expression gradually decreased with tumor progression from a normal epithelium to ovarian cancer tissues." (PMID 31615043, 2019).
ovarian carcinoma (continued). "Collectively, these observations suggested that ALDH1A2 plays a critical role in mediating the invasion activity of ovarian cancer cells." (PMID 31615043, 2019). "Treatment of ovarian cancer cells with the demethylating agent 5-Aza-CdR reversed the repression of ALDH1A2 expression." (PMID 31615043, 2019). "Taken together, these data suggest that ALDH1A2 expression is downregulated via gene methylation in ovarian cancer." (PMID 31615043, 2019). "To elucidate the clinical significance of ALDH1A2 in ovarian cancer patients, we compared ALDH1A2 expression levels by immunohistochemistry in benign, borderline, and malignant ovarian tumor tissues and in normal ovarian/fallopian epithelial tissues." (PMID 31615043, 2019). "In the present study, we identified ALDH1A2 as one of the most prominently downregulated ALDH genes in ovarian cancer cells, as compared to the expression in normal cells, based on microarray analysis." (PMID 31615043, 2019). "To elucidate the function of reduced ALDH1A2 in ovarian cancer progression, we constructed the pCMV-TagB-Flag-ALDH1A2 expression vector to overexpress ALDH1A2 in ovarian cancer cell lines." (PMID 31615043, 2019). "ALDH1A2 expression was restored in various ovarian cancer cell lines after treatment with the DNA methylation inhibitor 5-aza-2′-deoxycytidine." (PMID 31615043, 2019). "Functional studies revealed that forced ALDH1A2 expression significantly impaired the proliferation of ovarian cancer cells and their invasive activity." (PMID 31615043, 2019). "ALDH1A2 expression showed an obvious decrease with tumor progression from normal epithelium to ovarian cancer tissues." (PMID 31615043, 2019). "Due to the fact that the biological function of ALDH1A2 is exerted by the protein and not by the RNA, and OVCA3 cells display normal ALDH1A2 protein levels, this cell line represents an exception to the widespread ALDH1A2 downregulation in ovarian cancer." (PMID 31615043, 2019). "qRT-PCR demonstrated that the low levels of ALDH1A2 expression in ovarian cancer cell lines were reversed following treatment with the demethylation agent 5-Aza-CdR." (PMID 31615043, 2019). "Taken together, these observations suggest that the expression of ALDH1A2 is strongly downregulated in ovarian cancer." (PMID 31615043, 2019). "Furthermore, previous studies have proved the inhibitory effects of ALDH1A2 on the migratory and proliferative capabilities of ovarian cancer cells." (PMID 39440060, 2024). "Furthermore, functional assays confirm that the low expression of ALDH1A2 increases the potential of proliferation and invasion in ovarian cancer cells." (PMID 36694633, 2023). "Among them, ALDH1A2 is a symbolic marker of ovarian cancer cancer stem cell, and it may also be a potential marker of gastric cancer stem cells." (PMID 35659682, 2022). "Recent findings demonstrating that ALDH1A2 suppresses the proliferation of ovarian cancer cells may highlight its role in maintaining quiescence of the TIC population, as suggested by our studies." (PMID 33445692, 2021). "Thus, we first analyzed the DNA methylation status of the ALDH1A2 gene in ovarian cancer cell lines, RMG1, SKOV3, and OVCA433, which express low ALDH1A2 relative to levels in IHOSE8695, using conventional methylation-specific PCR analysis (MSP)." (PMID 31615043, 2019). "Among these isoforms, we further characterized the functional role of ALDH1A2 in ovarian cancer progression, because it was one of the most prominently downregulated genes, with approximately 50-fold lower expression levels in ovarian cancer cells than in normal cells." (PMID 31615043, 2019). "In addition, lower ALDH1A2 expression was correlated with poor prognosis in ovarian cancer patients." (PMID 31615043, 2019). "Furthermore, the ALDH1A2 gene was found to be hypermethylated via DNMT1 or DNMT3B in ovarian cancer cell lines, indicating that ALDH1A2 expression is regulated by epigenetic regulation via DNMT." (PMID 31615043, 2019).
ovarian carcinoma (continued). "Additionally, we focused on the role of ALDH1A2 as one of the most prominently downregulated genes in ovarian cancer." (PMID 31615043, 2019). "Taken together, our results suggest that ALDH1A2 might act as a tumor suppressor gene in ovarian cancer." (PMID 31615043, 2019). "In summary, we obtained novel evidence showing that low expression levels of ALDH1A2 are correlated with an early tumor stage and poor prognosis for ovarian cancer patients, and that its expression is negatively regulated by the methylation of ALDH1A2 via DNMT1 or DNMT3B." (PMID 31615043, 2019). "Furthermore, silencing DNA methyltransferase 1 (DNMT1) or 3B (DNMT3B) restored ALDH1A2 expression in ovarian cancer cell lines." (PMID 31615043, 2019). "Notably, hypermethylation of ALDH1A2 was significantly higher in ovarian cancer cell lines when compared to that in immortalized human ovarian surface epithelial cell lines." (PMID 31615043, 2019). "Next, we further confirmed the methylation status of the ALDH1A2 gene in a public dataset, Methylation and Expression database of Normal and Tumor tissues (MENT), and found that ALDH1A2 was significantly hypermethylated in ovarian cancer tissues compared to that in normal ovarian tissues." (PMID 31615043, 2019). "The low levels of ALDH1A2 in CEPI imply that a deficit of retinoic acid in these cells may be contributing to ovarian cancer by attenuation of the WNT signaling pathway." (PMID 20040092, 2009). "Besides, low ALDH1A2 expression is associated with shorter DFS and OS for ovarian cancer patients." (PMID 36694633, 2023). "However, the functions and prognostic value of ALDH1A2 in ovarian cancer progression remain unclear." (PMID 31615043, 2019). "Low expression of ALDH1A2 is an unfavorable prognostic biomarker for survival in PCa,128 HNSCC,129 breast cancer, ovarian cancer, and CC133 patients." (PMID 36694633, 2023). "It contains a potential gastric cancer cell (ALDH1A2 + and EPCAM +) completely derived from gastric cancer tissue, and ALDH1A2 is a marker of ovarian cancer cancer stem cell." (PMID 35659682, 2022). "ALDH1A2, ALDH1B1, and ALDH9A1 were downregulated in the ovarian cancer cells compared to the expression in HOSE cells, whereas ALDH3A1 was upregulated in the ovarian cancer cells." (PMID 31615043, 2019). "Therefore, we suggest that DNA methylation of ALDH1A2 and the expression of ALDH1A2 might serve as reliable markers for the early diagnosis of disease to improve the outcome for patients with ovarian cancer, considering that an accurate and timely diagnosis is often crucial for treatment selection." (PMID 31615043, 2019). "A recent study reported that over-expression of ALDH1A2 decreased cell growth and migration by down regulating STAT3 activation in ovarian cancer cells." (PMID 31534498, 2019). "Other investigators have reported, for the ovarian cancer cell lines YDOV-139, YDOV-157, YDOV-161, YDOV-13, YDOV-105, and YDOV-151, as compared with normal human ovarian epithelial cells, that the ALDH1A2 gene was the most prominent downregulated regarding ALDH family members." (PMID 37569466, 2023). "siRNA silencing of DNMT1 or DNMT3B restored the expression of ALDH1A2 and reduced methylation in ovarian cancer cells, whereas no significant changes in ALDH1A2 expression were observed upon knockdown of DNMT3A." (PMID 31615043, 2019). "Similarly, none of the malignant ovarian cancer cell lines examined produced a detectable amount of ATRA, which was attributed to a complete loss of ALDH1A2, and this loss was linked to tumour growth." (PMID 36768694, 2023). "ALDH1A2 suppresses the proliferation and migration of epithelial ovarian cancer cells by downregulating STAT3, and enhanced ALDH1A2-related signalling may provide new opportunities for therapeutic intervention in ovarian cancer." (PMID 36651035, 2023). "However, there are no reports regarding the epigenetic regulation of ALDH1A2 by DNMTs in human ovarian cancer." (PMID 31615043, 2019).
ovarian carcinoma (continued). "However, to our knowledge, there has been no report regarding the epigenetic regulation of ALDH1A2 in human ovarian cancer." (PMID 31615043, 2019). "However, it had not been determined whether reduced ALDH1A2 is relevant to the early diagnosis of ovarian cancer." (PMID 31615043, 2019).